PTX3 (pentraxin 3)
Diseases named in the same sentence as PTX3 in open-access papers (continued):
Sharing a sentence is not in itself a finding about the gene and the disease.
tumor (continued). "PTX3 expression is silenced through promoter hypermethylation in different types of cancers and may act as an oncosuppressor by modulating tumor-associated inflammation and/or by blocking protumor growth factors like various members of the FGF family." (PMID 31480336, 2019). "On the other hand, to further clarify whether the reduction of metastatic nodules in PTX3-depleted cells was associated with the inhibition of tumor growth, tumor cell proliferation was examined in parental and siPTX3 cells." (PMID 28489600, 2017). "PTX3 has been suggested to play an important role in tumor-associated inflammation." (PMID 27377307, 2016). "Hence, deficiency of PTX3 accelerated tumor development in mouse models of drug-induced cancerogenesis." (PMID 26074922, 2015). "Pentraxin 3 (PTX3), a modulator of tumor-associated inflammation, is known to be positively correlated with tumor grade and severity of malignancies, but its exact role remains unclear." (PMID 24457902, 2014). "Additionally, PTX3-associated complement components may cause tumor cells to express molecules aiding immune evasion." (PMID 39594709, 2024). "Mena loss also resulted in downregulation in the expression of genes that encode immunomodulatory secretory proteins that are part of the complement system, such as PTX3 and C3, suggesting that Mena may regulate immunosurveillance via the tumour-associated microenvironment." (PMID 36959177, 2023). "PTX-3, yet poorly understood, seems to be a pioneer in regulating cancer in both ways: it could settle an initial proper immune and inflammatory response and subsequently inhibit tumor progression, or it could increase metastatic risk." (PMID 36499628, 2022). "Therefore, one could assume that the expression and mutation of PTX3 are potential parts of tumor biology." (PMID 36139597, 2022). "However, from another perspective, PTX3 can act as an extrinsic oncosuppressor gene able to modulate complement-induced tumorigenesis and DNA damage associated with genetic instability of the tumor microenvironment." (PMID 34572075, 2021). "We postulate that PTX3 secretion in association with hyaluronan, particularly in the pan-stromal compartment, may entrap immune cells, thus preventing immune cells from accessing tumor cells to mount anti-tumor immunity." (PMID 34188166, 2021). "Our data indicate that PTX3 might play a significant pathogenic role in the development of this neoplasia through recruitment of the early components of Complement cascade with hampered activation of terminal Complement pathway associated with the upregulation of CD59." (PMID 33110136, 2020). "Pentraxin 3 (PTX3) could regulate the complement cascade by interacting with C1q and factor H (FH), and PTX3 deficiency resulted in complement activation and the recruitment of tumor-promoting macrophages." (PMID 31787848, 2019). "This indicates that PTX3-FH interaction could play a role in tumor-associated inflammation." (PMID 31428091, 2019). "Endovascular injection of adeno-associated virus harboring the PTX3 cDNA was used to block FGF2-mediated intimal thickening after balloon injury in the rat carotid artery whereas its retroviral/lentiviral transduction has been exploited to inhibit FGF activity in different tumor models." (PMID 30349543, 2018). "The latest research also shows that PTX3 deficiency triggers complement-dependent tumor-promoting inflammation, with enhanced tumor burden, macrophage infiltration, cytokine production, angiogenesis, and genetic instability, which increases tumor susceptibility." (PMID 28770376, 2017). "Formalin-fixed paraffin-embedded samples from tumor, peritumoral, and normal renal tissues were examined using confocal immunofluorescence microscopy to assess PTX3, IL-6, p21, and p16 expression." (PMID 41681886, 2026). "Pentraxin 3 (PTX3), an acute-phase protein, has a complex role in tumor progression, with its expression associated with disease severity." (PMID 41595551, 2025).
tumor (continued). "Recent studies emphasize the involvement of PTX3 in angiogenesis and inflammation, highlighting its participation in the crosstalk between tumor and immune cells." (PMID 41515435, 2025). "PTX3 is integral to the regulation of innate immunity, inflammation, and tumor dynamics through its dual function as both a pro-inflammatory and anti-inflammatory mediator depending on the context." (PMID 40313930, 2025). "Both tumor-promoting and tumor-suppressing activities have been reported for PTX3, with its function possibly varying depending on tumor type, cellular source, and surrounding environment." (PMID 41373493, 2025). "Initially identified in human umbilical vein endothelial cells and FS-4 fibroblasts in the 1990s, PTX3 is now known to be expressed in smooth muscle cells, myeloid dendritic cells, epithelial cells, and tumor cells." (PMID 40299501, 2025). "This differential expression highlights the potential of PTX3 as a therapeutic target and provides insights into the biological mechanisms within the tumor microenvironment." (PMID 40656950, 2025). "Based on existing literature, we describe how PTX3 acts as a pivotal regulator governing tumor fate." (PMID 41479916, 2025). "Transcriptomic analyses are unable to differentiate between PTX3 produced by tumor cells and that secreted by peritumoral microglia." (PMID 40656950, 2025). "A majority of ESCC cell lines and tumor samples show down-regulated PTX3 expression due to gene promoter hypermethylation." (PMID 41479916, 2025). "The conducted study was designed to determine the impact of CAPE on the selected cytokines and metalloproteinases as well as PTX-3, which are connected with tumor microenvironment and metastasis." (PMID 41515435, 2025). "GBM stem-like cells can further drive malignant DC transformation via ZNF148/PTX3 signaling, while tumor-derived exosomes induce ferroptosis in DCs through modulation of the NRF2/glutathione peroxidase-4 (GPX4) pathway, contributing to tumor progression." (PMID 40948940, 2025). "Recent in vivo and in vitro studies indicate that PTX3 is involved in cancer-related inflammation and plays a role in various aspects of cancer progression, including tumor onset, angiogenesis, metastatic spread, and cancer immune modulation." (PMID 41373493, 2025). "In 2017, they further identified two enhancers of PTX3, whose methylation inactivated PTX3, counteracting its tumor-suppressive function in CRC." (PMID 41479916, 2025). "The correlation between PTX3 expression and immune cell infiltration further emphasizes its involvement in the tumor microenvironment and immune regulation." (PMID 40656950, 2025). "In 2015 and 2017, two studies demonstrated the tumor-suppressive role of PTX3 in CRC, revealing some common findings." (PMID 41479916, 2025). "Intriguingly, PTX3 can also act as an extrinsic tumor suppressor, counteracting macrophage-mediated, complement-dependent tumor-promoting inflammation." (PMID 41515435, 2025). "The analysis of PTX3 expression across various cancer datasets provides strong evidence for its role in tumor biology." (PMID 40656950, 2025). "While PTX3 enhances the body’s defense to clear these pathogens, it also plays an indispensable role in regulating inflammation, tissue remodeling, and anti-tumor responses." (PMID 40313930, 2025). "PTX3 interacts with immune components, influencing tumor progression and the inflammatory microenvironment in cancers." (PMID 40656950, 2025). "Blood samples were analyzed for pentraxin-3 protein levels, interleukins, microRNA, and circulating tumor cells." (PMID 38254906, 2024). "Most of the members can also activate the PI3K/AKT/mTOR pathways, which implies interference with the normal cell cycle, with PTX3 particularly identified to have unique receptors that mediate tumor progression." (PMID 38730589, 2024).
tumor (continued). "In additional three datasets collected for studying PCa metastasis, an elevation of PTX3 expression was consistently detected in metastatic tumours as compared to primary cancer samples." (PMID 39187920, 2024). "PTX3 appears to promote oncogenic inflammatory effects by modulating the tumor microenvironment, ultimately contributing to protumoral processes." (PMID 39594709, 2024). "In line with the observations that silencing of PTX3 expression via an epigenetic manner was detected in some cancer types, a tumour suppressor function of PTX3 was demonstrated in gene knockout mice." (PMID 39187920, 2024). "Recent studies suggest PTX3’s involvement in tumor progression, including metastasis and invasion, in multiple cancer types." (PMID 38730589, 2024). "This tumorigenic role has also been observed in in vivo experiments, in which the upregulation of PTX3 was found to promote the proliferation and metastasis of tumor cells." (PMID 39594709, 2024). "PTX3 is well-known to promote cell proliferation, angiogenesis, and tumor invasion in a variety of cancers, including breast cancer, prostate cancer, liposarcoma, pancreatic cancer, and hepatocellular carcinoma." (PMID 38730589, 2024). "Lastly, STAT3, a transcription factor that regulates downstream signals for cell proliferation and apoptosis, has been found to promote tumor cell growth through PTX3." (PMID 39594709, 2024). "In this context, Liu and colleagues discovered that SPOCD1 positively regulates the expression of PTX3 in GB, promoting tumor growth." (PMID 38730589, 2024). "The expression levels of the PTX3 gene and protein appear to vary significantly across different tumor types and patient populations." (PMID 39594709, 2024). "PTX3 plays a crucial role in regulating tumor cell migration and metastasis through various mechanisms." (PMID 39594709, 2024). "Although PTX3 was recognized as a molecule predominantly associated with cells of mesenchymal origin in PDAC, two clusters of tumor cells (Tumor 3, Pan-Ck+ PTX3+; Tumor 5, Pan-Ck+ Ck-7+ PTX3+) were identified based on its high expression." (PMID 39575252, 2024). "We found that PTX3 levels of PCa tumour samples were higher than that of normal adjacent prostate tissues in GSE59745." (PMID 39187920, 2024). "The evidence suggests that PTX3 holds significant potential as a therapeutic target due to its pivotal role in various signaling pathways and tumor metastasis." (PMID 39594709, 2024). "As observed in other tumors, PTX3 produced by cancer cells promote tumor progression by promoting invasiveness and migration." (PMID 39575252, 2024). "Conversely, PTX3 protein has also been reported to enhance tumor aggressiveness and reduce the host’s immune response against tumor cells." (PMID 39594709, 2024). "This study suggested that JUN participates in cell autophagy modulation by regulating PTX3 expression, promoting tumor progression." (PMID 38730589, 2024). "When compared to the corresponding controls, PTX3 downregulation resulted in a significant decrease of MDA-MB-231 shPTX3 tumor growth." (PMID 37749607, 2023). "The tumorigenicity assay indicated an obvious increase in the tumor volume of mice that were subcutaneously implanted with PTX3‐overexpressing t‐DCs compared with the control group." (PMID 37063077, 2023). "As a secreted protein, PTX3 can be produced and released by both tumor and stroma cells, depending on tumor type." (PMID 37749607, 2023). "Relevant to this point, our data show for the first time that PTX3 exerts its pro-tumor activity in TNBC by activating TLR4/IRAK1/NF-kB signaling in tumor cells." (PMID 37749607, 2023). "In conclusion, we demonstrated that PTX3 is highly expressed in the most aggressive TNBC subtype and that PTX3 expression by tumor cells fosters the tumorigenic potential of TNBC." (PMID 37749607, 2023). "Some other authors revealed the involvement of PTX3 in the tumor microenvironment in promoting cancer metastasis, invasion, and stemness." (PMID 38136377, 2023).
tumor (continued). "A high/preferential expression of PTX3 occurs in the tumor cell subpopulations (CC_TNBC) characterized by the expression of Keratin 8 (KRT8) and high genomic instability." (PMID 37749607, 2023). "PTX3 expression was significantly lower in patients surviving with tumors than in tumor free patients, revealing a potential correlation between PTX3 and tumor recurrence." (PMID 37025408, 2023). "On the other hand, PTX3 has been shown to promote cell migration and invasion in some experimental tumor models, its expression levels being correlated with tumor progression in different human tumor types." (PMID 37749607, 2023). "PTX3 deficiency further leads to the up‐regulation of CCL2 expression and promotes tumour recruitment of macrophages." (PMID 36872292, 2023). "In silico and experimental data indicate that PTX3 is mainly produced by tumor cells in TNBC and that its expression levels correlate with tumor stage." (PMID 37749607, 2023). "The pattern recognition receptor long pentraxin-3 (PTX3) plays conflicting roles in cancer by acting as an oncosuppressor or as a pro-tumor mediator depending on tumor context." (PMID 37749607, 2023). "Conversely, grafting of PTX3 overexpressing MDA-MB-468 PTX3 cells into the mammary fat pad of immune-compromised mice resulted in an increased tumor burden in respect to mock lesions." (PMID 37749607, 2023). "Altogether, these data shed light on the role of tumor-produced PTX3 in TNBC and uncover the importance of the PTX3/TLR4 axis for therapeutic and prognostic exploitation in TNBC." (PMID 37749607, 2023). "Tumour-promoting and tumour-suppressive roles for PTX3 have been described, while elevated levels of PTX3 correlate with either poor prognosis or grade of malignancy in several cancers." (PMID 36959177, 2023). "In several kinds of human tumours, PTX3 expression is inhibited by methylation of promoter and enhancer regions of human n‐pentaginin‐3, an important component of humoral immunity in innate immunity." (PMID 36872292, 2023). "Accordingly, Western blot analysis performed on samples from triple negative (TN), triple positive, ER+/PR+ and HER2+ tumor biopsies confirmed the prevalent expression of PTX3 in basal-like TNBC." (PMID 37749607, 2023). "Researchers have proven that PTX3 acts as an extrinsic oncosuppressor gene both in mouse and human models (cancer cell lines), and the complement system is a key component of tumor-promoting cancer-related inflammation." (PMID 38136377, 2023). "The impact exerted by PTX3 modulation in TNBC cells was further assessed in vivo by orthotopic tumor models in immune-compromised mice." (PMID 37749607, 2023). "In order to understand the relative contribution of tumor and stromal/immune cells to PTX3 production in TNBC, analysis of single cell RNA sequencing data was performed on tumor samples obtained from TNBC patients." (PMID 37749607, 2023). "Preclinical studies have proven that targeting pancreatic stellate cells with ATRA (all-trans-retinoic acid) in combination with specific chemotherapy (gemcitabine-nab-paclitaxel) leads to tumor suppression, possibly by modulating PTX-3 expression." (PMID 36499628, 2022). "Some studies have shown that Pentraxin-3 (PTX3) is an immune modulator thought to play a role in tumor angiogenesis, proliferation, and escape of tumors." (PMID 36046345, 2022). "PTX3 is engaged in tumor cell proliferation, angiogenesis, metastasis and immune modulation in tumors." (PMID 36290747, 2022). "PTX3 is a double‐edged sword in carcinogenesis, which depends on the specific tumor microenvironment." (PMID 35855654, 2022). "In conclusion, the modified PTX3 peptide P2rdAD9 effectively inhibited tumour growth and metastasis and increased the efficacy of chemotherapeutic drugs." (PMID 35090088, 2022).
tumor (continued). "Nevertheless, PTX-3 levels decreased after tumor resection, but again increased in cases of recurrence, thus in cases of high-grade inflammation, hyperactive angiogenesis and inhibition of cellular apoptosis occurred, as other researchers have assessed." (PMID 36499628, 2022). "In vitro treatment with trabectedin decreased the production of CCL2, CXCL8, IL-6, VEGF and PTX3 by myxoid liposarcoma (MLS) primary tumor cultures and/or cell lines, and freshly isolated ovarian cancer cells from ascites." (PMID 35299737, 2022). "PTX3 was a hazardous prognostic marker in 18 independent tumor cohorts and a favorable prognostic marker in three independent tumor cohorts regarding OS." (PMID 35855654, 2022). "Emerging evidence has demonstrated that PTX3 facilitated cellular proliferation and conferred resistance to apoptosis by altering cell cycle signaling, thereby, promoting tumor escape from immunosurveillance, in support of our observation." (PMID 36139597, 2022). "Collectively, we suggest that clinicians should pay particular attention to tumor patients with high PTX3 expression and should make specific and deliberative treatment choices." (PMID 36139597, 2022). "Current reports show that PTX3 is a product of both neoplastic and stromal cells, changing the tumor microenvironment." (PMID 36290747, 2022). "On the other hand, PTX-3 sustains cellular migration and proliferation and dysregulates mitogenic signaling pathways; therefore, encouraging tumor escape from immune responses." (PMID 36499628, 2022). "The role of PTX3 in immunotherapy should be further validated in clinical and in cell experiments such as coculturing tumor cells with immune cells using the interference for PTX3." (PMID 36139597, 2022). "Although these data together imply the pro‐tumourigenic role of PTX3 in tumour progression, as we suggested, these findings are in sharp contrast to other reports in which PTX3 was found to exert a tumour‐suppressive role." (PMID 35090088, 2022). "Interaction network and enrichment analyses revealed that PTX3 participated in tumor immuno-related progression." (PMID 36139597, 2022). "The researchers emphasize that the effect of PTX3 will be closely dependent on the type of tumor and its microenvironment." (PMID 36290747, 2022). "Several studies have shown that PTX3 can inhibit or promote angiogenesis, depending on the context and the tumor." (PMID 36555812, 2022). "PTX3 is involved in tumor progression in multiple types of cancer and has also been identified as an independent prognostic predictor of cancer." (PMID 35664334, 2022). "Analysis of complement system activation on tumor tissues showed the co-expression of PTX3 with C1q, C3aR, C5R1, and CD59." (PMID 35651807, 2022). "First, we found that PTX3 showed abnormal expression and correlated with the prognosis of tumor patients." (PMID 36139597, 2022). "Concurrently, our GSEA results implied that PTX3 engaged in tumor immune and metabolism pathways such as the “inflammatory response”, “complement”, “KRAS signaling”, “arginine and proline metabolism”, and “Toll-like receptor signaling pathway”." (PMID 36139597, 2022). "Based on immunohistochemical analysis of human tumor specimens, increased PTX-3 hypermethylation was identified in the early stages of esophageal carcinogenesis rather than in advanced stages." (PMID 36499628, 2022). "Our analyses showed that PTX3 was aberrantly expressed in most tumors and was significantly related to prognosis and tumor stage." (PMID 36139597, 2022). "In in vivo experiments, using a xenograft mouse model of human MLS, a marked reduction of human CCL2, CXCL8 and PTX3 after trabectedin administration was observed, demonstrating that this effect on tumor cells occurs also in vivo." (PMID 35299737, 2022). "The ROC analysis showed that PTX3 achieved good prediction efficacy to distinguish tumor from normal (AUC > 0.80) for BRCA, CHOL, COAD, KICH, LUSC, and THCA." (PMID 36139597, 2022).